CSMD1 (CUB and Sushi multiple domains 1)
Diseases named in the same sentence as CSMD1 in open-access papers (continued):
Sharing a sentence is not in itself a finding about the gene and the disease.
tumor (continued). "Moreover, Paclitaxel sensitivity is lower in the mutant CSMD1 group and CSMD1 mutation is associated with tumor invasion of immune cells with more follicular helper T cells and fewer resting state dendritic cells." (PMID 37598390, 2023). "In addition, the anti-tumor activity of CSMD1 has been associated with activation of the Smad signaling pathway." (PMID 35412956, 2022). "Furthermore, a large-scale genomic study on HNSCC cancers demonstrated an association between CSMD1-inactivation and tumour immunity." (PMID 36553598, 2022). "Our study unravels one possible underlying molecular mechanism of CSMD1 tumor suppressor function and may provide novel avenues for design of better treatment." (PMID 34404439, 2021). "We sought to assess the association between CSMD1 inactivation and tumor immunity." (PMID 30545040, 2018). "This high NS/S ratio in CSMD1 mutant alleles (15∶1) approaching clonal dominance is consistent with the Darwinian model of tumor sub-clone development and positive Darwinian selection for nonsynonymous mutations within the primary tumor." (PMID 23505554, 2013). "CSMD1 variant allele sampling by deep sequencing may be an attractive method for identifying early-stage neoplasia." (PMID 23505554, 2013). "The alternative hypothesis is that selective pressure drove the accumulation of multiple CSMD1 nonsynonymous variants within the same tumor, possibly residing in separate subclones." (PMID 23505554, 2013). "These pathways may be associated with the tumor suppressor role of CSMD1." (PMID 27756250, 2016). "Losses in the 8p23.1 region, which contains multiple genes related to immune function, T-cell regulation (TNKS, PPP2CB,) and tumor suppression (CSMD1, MSR), were enriched in MEITL (61% versus 7%, p = 0.02)." (PMID 41057685, 2026). "Another critical gene implicated in cancer progression is CUB and Sushi Multiple Domains 1 (CSMD1), a tumor suppressor gene which is involved in regulatory cellular functions and is lost in approximately 40% of HNSCC tumors." (PMID 40650111, 2025). "Another protein, CSMD1, acts as a tumour suppressor gene, while microRNA‐10b drives GC cell invasion and metastasis by inhibiting CSMD1, activating the NF‐κB pathway, and upregulating c‐Myc, cyclin D1, and epithelial–mesenchymal transition (EMT) markers." (PMID 40999796, 2025). "C2 displayed amplifications in MYC and NOTCH2, potentially linked to aggressive tumor phenotypes, along with deletions in RB1 and CSMD1, which are associated with tumor suppressor loss." (PMID 41568381, 2025). "Nevertheless, the expression levels and functional implications of CSMD1 concerning the tumour's location remain poorly understood." (PMID 40999796, 2025). "CSMD1 is an integral membrane component affecting several processes, including tumour suppression, complement-mediated synaptic pruning, and immune-related signalling." (PMID 40157903, 2025). "Signal intensity measurements of both CSMD1 and total P65 were also determined in the tumor region of mice injected with either RCAS- PDGFB + shGL2 or RCAS- PDGFB + shCsmd1." (PMID 38561856, 2024). "The downregulation of CSMD1 expression correlated with reduced overall and disease-free survival, elevated tumor grade, wild-type IDH genotype, and intact 1p/19q status." (PMID 38561856, 2024). "Our analysis indicated that CSMD1 is suppressed within the tumor region of the brain injected with RCAS-PDGFB + shCsmd1 when compared to the tumor region of the mice injected with RCAS-PDGFB + shGL2." (PMID 38561856, 2024). "CSMD1 gene expression has multiple tumor-suppressing functions through the SMAD pathway (promotes apoptosis, reduces cell proliferation and migration), likely contributing to trophoblast cell regulation during placentation in first trimester." (PMID 39152463, 2024).
tumor (continued). "In particular, CSMD1 and ANKRD36C genes showed significant mutation co-occurrence across patients in the S-I AEG tumor subtype." (PMID 36774361, 2023). "The observed mutations of genes involved in antitumor immune responses were mostly polyclonal, but mutations in CSMD1, MUC16 and TTN occurred as clonal alterations, suggesting again a clonal advantage for those tumor cells." (PMID 36980598, 2023). "The most significantly enriched term in the obtained results was “mRNA processing” (GO:0006397), and the input genes were obtained from DCGs with CSMD1, which has a tumor-suppressive function." (PMID 36077026, 2022). "qRT-PCR and Western blot results exhibited abundant expression of miR-642b-3p and Smad7 yet poor expression of CSMD1 and Smad4 in the tumor tissue of mice treated with miR-642b-3p mimic, the effects of which were undermined by CSMD1." (PMID 35412956, 2022). "Following the in vitro researches, in vivo experiments confirmed the anti-tumor power of down-regulated miR-642b-3p and up-regulated CSMD1 gene in the context of GC." (PMID 35412956, 2022). "CSMD1 is involved in such well-known tumor pathways as NF-κB pathway and epithelial-mesenchymal transition pathway." (PMID 35321246, 2022). "Subsequently, CSMD1, a frequently reported tumor suppressor, was suggested to be the putative target gene of miR-642b-3p by bioinformatics analysis." (PMID 35412956, 2022). "Subsequently, inhibition of miR-642b-3p was found to impede the proliferative activities of GC cells in vitro as well as the tumor growth in vivo through up-regulation of CSMD1 expression, which was involved in the activation of Smad signaling pathway." (PMID 35412956, 2022). "It has also been suggested that CSMD1 can impede tumor formation through the Smad signaling pathway, which has a role to confer in the pathophysiological processes of GC." (PMID 35412956, 2022). "Versus CSMD1 alone, CSMD1 + miR-642b-3p mimic resulted in more obvious increase in tumor volume and weight." (PMID 35412956, 2022). "CUB and Sushi Multiple Domains 1 (CSMD1), a tumour suppressor gene, encodes a large membrane-bound protein including a single transmembrane domain." (PMID 36553598, 2022). "In conclusion, we have characterized one novel mechanism of tumor suppressor activity of CSMD1 and we have identified EGFR as the mediator of this action." (PMID 34404439, 2021). "In the current study, we report for the first time the direct interaction of EGFR with the tumor suppressor CSMD1, which leads to attenuation of EGFR signaling due to altered trafficking of the receptor." (PMID 34404439, 2021). "Since Csmd1 is a known tumour suppressor gene it would be interesting to explore the role of Csmd1 in cancer in vivo, to determine if the in-vitro changes observed in this study are also involved in regulating cancer development." (PMID 33530646, 2021). "Last, we leveraged the scRNA-seq data from XYZeq to visualize how individual MSCs expressed Tshz2 and Csmd1, two genes of divergent function that are spatially variable with respect to the tumor in the spleen." (PMID 33883145, 2021). "Surprisingly, the expression of CSMD1 and SENP3 was significantly decreased in tumor tissues (P-value < 0.05, 3D for CSMD1, 3F for SENP3)." (PMID 33558447, 2021). "More than one CSMD1 alterations was found in 22/57 (38.6%) tumours, and 5/57 BCCs (8.8%) harboured more than six CSMD1 somatic mutations." (PMID 34168209, 2021). "The Cub Sushi Multiple Domains-1 (CSMD1) protein is a tumour suppressor which has been shown to play a role in regulating human mammary duct development in vitro." (PMID 33530646, 2021). "The significance of such enrichment reaches p < 10−58 for CACNA1C and SNX29 from the Network of Cancer Genes, and p < 10−61 for WWOX and CSMD1 from the Tumor Suppressor Gene Database." (PMID 33741065, 2021).
tumor (continued). "The immune infiltration analysis showed that the anti-tumor immune cells were upregulated and that the tumor-promoting immune cells were downregulated in the CSMD1-mut samples." (PMID 34828321, 2021). "In relation to cancer, CSMD1 has been identified as a tumour suppressor with previous studies identifying the chromosome location 8p23 as an area deleted in various cancers, such as breast, head and neck and colorectal." (PMID 33530646, 2021). "In the multivariate analysis, copy-number losses (CNLs) in chromosome B1 (1–23 Mb) harbouring several tumour-repressors (e.g. CSMD1, MTUS1, MSR1, DBC2, and TUSC3) negatively influenced DFS." (PMID 31969654, 2020). "On the other hand, common CNLs negatively influencing survival intervals harboured important tumour suppressors (e.g. CSMD1, MTUS1, MSR1, DBC2, and TUSC3) and genes enriching biological processes that would normally prevent cellular movement." (PMID 31969654, 2020). "There are no genes identified in or near the HPV integration sites in the 2q14.2 regions, while the HPV integration in 8p23.2 disrupted a very large gene CSMD1 which has been reported as a potential tumor suppressor from different cancers." (PMID 30975103, 2019). "We used siRNA-mediated silencing of CSMD1 in order to further clarify the role of CSMD1 in tumor cell proliferation and invasion." (PMID 27756250, 2016). "Forty-five paired human HCC and adjacent non-tumor tissues were collected for qRT-PCR and immunohistochemistry analysis of miR-10b and CUB and Sushi multiple domains 1 (CSMD1), respectively." (PMID 27756250, 2016). "This region of Chromosome 8 has also been identified as a peak region of deletion across multiple tumor types and contains the tumor suppressor CSMD1." (PMID 26772196, 2016). "CSMD1 expresses mainly in epithelial cells and exhibits anti-tumor activity through activation of the Smad pathway." (PMID 25927497, 2015). "The putative tumor suppressor CSMD1 was already shown to diminish complement activation at the level of C3b." (PMID 26480818, 2015). "The results of RT-PCR showed that the expression levels of CSMD1 mRNA were down-regulated in HepG2, SK-hep-1 and MHCC-97H compared with that in HL-7702, indicated that CSMD1 played a role of tumor suppression gene." (PMID 26076954, 2015). "One tumor did have CSMD1 mutation allele concentrations that were less than the KRAS mutant allele concentration, perhaps indicating that the CSMD1 mutations in this tumor occurred after the KRAS mutations." (PMID 23505554, 2013). "The Cub and Sushi Multiple Domains 1 (CSMD1) gene is a novel candidate tumor suppressor gene located on the p arm of chromosome 8 (2792875...4852328)." (PMID 23505554, 2013). "Several candidate tumor suppressor genes that are less known to be implicated in human cancers include DOCK5 and CSMD1 map to this region." (PMID 22355333, 2012). "CSMD1 is a tumor suppressor gene that maps to chromosome 8p23, a region deleted in many tumor types." (PMID 22558405, 2012). "CSMD1 functions as a complement inhibitor, while also having a direct tumor suppression effect." (PMID 38561856, 2024). "Moreover, there was a clear trend for the downregulation of CSMD1 in the tumor region of mice injected with RCAS-PDGFB + shCsmd1 compared to RCAS-PDGFB + shGL2." (PMID 38561856, 2024). "The complement inhibitor CSMD1 acts as a tumor suppressor in various types of solid cancers." (PMID 38561856, 2024). "Tumor driver gene mutations and wild-type samples used for KM analysis showed better survival outcomes in samples with CSMD1 and ERBB3 wildtype compared to samples with CSMD1 and ERBB3 mutations." (PMID 37063290, 2023). "Overall, miR-642b-3p acts as an oncomiR promoting tumor development in GC through suppressing CSMD1 expression and inactivating the Smad signaling pathway, which may enable the development of new therapeutic strategies for treatment of GC." (PMID 35412956, 2022).
tumor (continued). "Another study discovered that miR-642b-3p acts as an oncomiR that promotes tumour progression in GC by repressing CSMD1 expression and inactivating the Smad signalling pathway, which could contribute to the development of potential therapies for GC treatment." (PMID 36553598, 2022). "Additionally, tumor volume and weight were increased in mice treated with miR-642b-3p mimic but they were decreased upon treatment with CSMD1." (PMID 35412956, 2022). "Human Cub and Sushi Multiple Domains 1 (CSMD1) is a novel candidate tumor-suppressor gene." (PMID 36291785, 2022). "Therefore, in this investigation, we illustrated that miR-642b-3p directly bound to CSMD1 gene, thereby exerting tumor-promoting function in GC." (PMID 35412956, 2022). "However, there is only a handful of reports experimentally confirming the tumor suppressing properties of CSMD1." (PMID 34404439, 2021). "Tumor-promoting immune cells including regulatory T (Treg) cells (p = 0.007), M2 macrophage cells (p = 0.037), and endothelial cells (p = 0.007) had lower proportions in the CSMD1-mut group." (PMID 34828321, 2021). "The increased complement deposition on tumour cells due to CSMD1 deletion might be the link to a favourable Mandard TRG, but this needs further investigation." (PMID 33506581, 2021). "However, we found that spleen/tumor MSCs expressed lower levels of Csmd1 but higher levels of Tshz2 in closer proximity to the tumor." (PMID 33883145, 2021). "On the other hand, CNLs in FCA B1 1–23 Mb (human homologue region located in HSA 8p) were significant in multivariate analysis and harboured multiple tumour suppressors (e.g. CSMD1, MSR1, MTUS1, and TUSC3) previously correlated with poor prognosis in HBCs15,19,23,27,70." (PMID 31969654, 2020). "Furthermore, expression of CSMD1 in vivo resulted in diminished formation of metastatic foci in a xenograft model likely due to impaired rate of escape of tumor cells from the primary tumor." (PMID 27764775, 2016). "We did not observe differences in lymphocyte infiltration in tumors sections (staining for CD45; data not shown), indicating that the tumor-suppressing activities of CSMD1 are not linked to its complement inhibitory function." (PMID 27764775, 2016). "Therefore, the assumption that CSMD1 acts as tumor suppressor gene remains unsubstantiated with a direct experimental approach." (PMID 27764775, 2016). "Thus, we studied the effect of CAFs and control fibroblasts on tumor cells with modified levels of CSMD1 on the survival and proliferation using direct physical contact between cancer cells and fibroblasts." (PMID 27764775, 2016). "Taken together, mounting evidence indicates that CSMD1 functions as a tumor suppressor gene." (PMID 27756250, 2016). "Importantly, HepG2 cell migration and invasion were also induced after CSMD1 knockdown, suggesting that CSMD1 plays a functional role as a tumor suppressor gene." (PMID 27756250, 2016). "Their results supported the idea that CSMD1 was a tumor suppressor gene." (PMID 26076954, 2015). "In contrast to our earlier studies, we did not observe a significant relationship between CSMD1 somatic mutation status and tumor stage in this series of samples." (PMID 23505554, 2013). "Interestingly, 8p23.2 was also more frequently deleted in BRCA mG3 tumors although the EMT signature was upregulated in mG1, suggesting that CDH1 inactivation and CSMD1 deletion might be two independent mechanisms for tumor metastasis." (PMID 40740860, 2025). "Thus, CSMD1 was implied to act as a putative tumor suppressor gene." (PMID 27764775, 2016).
tumor (continued). "Unlike microRNA-7, microRNA-10b increased the malignant phenotype of tumor cells by suppressing the expression of CUB and sushi multiple domains protein 1 (CSMD1) and up-regulating the expression of c-MYC, cyclin D1, and EMT markers." (PMID 36439439, 2022). "The IHC analysis of ARID1A, CSMD1, and SENP3 proteins showed that the expression level of all the three genes was significantly different between tumor and paracarcinoma tissues (P < 0.05)." (PMID 33558447, 2021). "Herein, we focused on ARID1A, CSMD1, and SENP3 during tissue microarray analysis of 180 HCC samples paired with tumor and paracarcinoma tissues as a replication population." (PMID 33558447, 2021). "We provide evidence that inactivation of CSMD1 occurs very early in HNSCC and provide functional evidence to support a tumour suppressor role." (PMID 31427592, 2019). "Moreover, many studies have indicated CSMD1 could be a tumor suppressor gene." (PMID 26076954, 2015). "Among the genes that reside at this region is the CUB and Sushi Multiple Domains 1 gene (CSMD1), which is a tumor suppressor gene that codes for multiple domain complement regulatory and adhesion protein." (PMID 24694993, 2014). "To assess the independent prognostic value of CSMD1 gene expression in adjuvant treated TNBC patients, we performed multivariable Cox regression analysis adjusting for tumor size (≤ 20 mm, > 20 mm), tumor grade, and lymph node status (N0, N +) using OS and IDFS as the clinical endpoints." (PMID 34404439, 2021). "Interestingly, eight among the overlapped hypermethylated genes (WT1, PAX6, GNAS, EPB41L1, CSMD1, CPEB1, RERG, and SMAD6) were previously reported to exhibit tumor suppressive functions." (PMID 34462486, 2021). "Anti-tumor immune cells including CD4+ Th1 cells (p = 0.009), NK cells (p = 0.033), M1 macrophage cells (p = 0.007), and plasmacytoid dendritic cells (PDC) (p = 0.010) had higher proportions in the CSMD1-mut group." (PMID 34828321, 2021). "Recurrent SVs in CSMD1, WWOX, ERC1, PDE4D and SHANK2 were also identified in five tumor samples." (PMID 32617189, 2020). "CSMD1, CDKN2A, NOTCH1, and SMAD4 are known to be tumor-suppressor genes." (PMID 29340043, 2017). "Last but not least, low CSMD1 expression is closely related to high tumor grade in a variety of cancers." (PMID 27756250, 2016). "Thus, these inactivating CSMD1 mutations may possibly reveal their apparent phenotypic influence on tumor pathology only after mutations in critical gatekeeper genes produce a cell population in which the absence of normal CSMD1 creates a pathophysiological effect." (PMID 23505554, 2013). "CSMD1 inactivation might be related to HPV and tumor immunity." (PMID 30545040, 2018). "CSMD1 was downregulated in a grade-dependent manner in the studied patient cohorts, and it was nearly absent in GBM, classified as a “cold” tumor due to a lack of infiltrating T cells." (PMID 38561856, 2024). "Within this region, there are established tumor suppressors (DLC1, DOK2 and LZTS1), as well as potential tumor suppressor genes (CSMD1, MTUS1, and MSR1), and many other genes not established in cancers." (PMID 35994499, 2022).